SIGLEC7 (sialic acid binding Ig like lectin 7)
Diseases named in the same sentence as SIGLEC7 in open-access papers (continued):
Sharing a sentence is not in itself a finding about the gene and the disease.
tumor (28 papers, 2020 to 2025). "Gene function analysis revealed that SIGLEC7 is primarily involved in immune and inflammatory responses and is strongly negatively correlated with tumor-associated immune regulation." (PMID 39211050, 2024). "Researchers have confirmed that SIGLEC7 drives tumor-associated macrophages to promote tumor development in pancreatic cancer." (PMID 39211050, 2024). "In KEGG analysis, SIGLEC7 was mostly associated with tumor immune processes, although there were pathways promoting tumor expression." (PMID 39211050, 2024). "Previously, our lab and others have shown that Siglec‐7 clusters on the membrane at the site of interaction with a tumor cell, which is associated with Siglec‐7 signalling." (PMID 39246414, 2024). "Siglec‐7, an inhibitory immune receptor on human natural killer cells, represents a potential target for tumor immunotherapy." (PMID 40285643, 2025). "Tumor weight also was significantly lower in the anti-Siglec7/9 mAb treated group compared with IgG controls at the end of the treatment period." (PMID 39436703, 2024). "Antibodies against SIGLEC-7 and SIGLEC-9 can suppress the conversion of macrophages into tumor-associated macrophages and reprogram the immunosuppressive tumor microenvironment, enhancing anti-cancer immunity." (PMID 39349440, 2024). "The ability of the different tumor cell lines to induce Siglec‐7 signalling was assessed, using our recently established chimeric Siglec‐7 (chSiglec‐7) Jurkat/MA signalling tool." (PMID 39246414, 2024). "By 25 days, PC3 tumor volumes were significantly smaller in the anti-Siglec7/9 mAb treated group compared with the IgG controls." (PMID 39436703, 2024). "Siglec‐7 and Siglec‐9 ligands were present in both TN and ER+ tumor subtypes in situ as well by a set of TN and ER+ tumor cell lines." (PMID 39246414, 2024). "We only briefly analyzed the reasons for SIGLEC7 promoting tumor progression, and further exploration of deeper mechanisms is needed in the future." (PMID 39211050, 2024). "In cancer, SIGLEC7 is expressed on most immune cells and can favor immune evasion in cancer, in addition to its contribution to tumor growth and progression." (PMID 37064098, 2023). "Our findings showed that dramatic downregulation of exosomal PD-L1, E-cadherin, ULBP1, ULBP3, MICA, MICB, Siglec7 and significant upregulation of exosomal PD-1 and IFN-gamma were associated with tumor regression." (PMID 36741391, 2022). "Inhibitory receptor Siglec7 interacts with sialoglycosides, which are frequently overrepresented on the surface of tumor cells." (PMID 34834534, 2021). "The synthetic ligands can weaken the interactions between Siglec7 and its tumour ligands and, hence, inhibit cancer immune evasion." (PMID 32322597, 2020). "Firstly, Sia, the ligand of Siglec7 and Siglec9 expressed on the surfaces of tumour cells, is correlating with the immune evasion in cancer." (PMID 32322597, 2020). "Siglec7 and Siglec9 expressed on NK cells and their ligands play important roles in promoting the process of proliferation and migration of tumour cells." (PMID 32322597, 2020). "The fact that tumour cells escape from NK cell attack through the interaction of cell surface sialyl-decoration with Siglec7 and Siglec9 on NK cells makes the two lectins promising target in antitumor drug development." (PMID 32322597, 2020). "Finally, TPD can also target POI from the tumour microenvironment which play an essential role in tumour growth, such as the glycoimmune checkpoints Siglec‐7 and Siglec‐9." (PMID 40266852, 2025). "Importantly, multiple TN tumor cell lines were able to trigger chSiglec‐7 signalling, but only one ER+ cell line induced Siglec‐7 signalling." (PMID 39246414, 2024). "Siglec‐7 and Siglec‐9 ligands were found to be expressed in both TN and ER+ tumor sections." (PMID 39246414, 2024).
tumor (continued). "Releasing the brake on effector cells such as NK cells and cytotoxic T cells by blocking Siglec‐7 could potentially increase tumor control, as it has previously been shown that Siglec‐7 can inhibit NK cell cytotoxicity and effector T cell functions." (PMID 39246414, 2024). "Therefore, we studied the expression and signalling inducing capacity of Siglec‐7 and Siglec‐9 ligands as present on a set of TN and ER+ tumor cell lines." (PMID 39246414, 2024). "Moreover, recent experiments conducted in a humanized immunocompetent mouse model demonstrated that blocking SIGLEC7 or SIGLEC9 reduces tumor burden in vivo, providing support for the use of anti-SIGLEC antibodies as a means to enhance anti-tumor immunity." (PMID 38311726, 2024). "Accordingly, such tumor cells inhibit the cytotoxic activity of NK cells by cross-linking Siglec7." (PMID 34834534, 2021). "Interestingly, through our analysis, SIGLEC7 showed higher negative regulation correlation than positive regulation in the categories of regulation of immune response, regulation of immune effector process, and regulation of responses to tumor cells." (PMID 39211050, 2024). "Phosphosites from immune system-associated proteins (e.g., IL3RA, PECAM1, PTPN1, SIGLEC7, and JUP) showed an overall higher phosphorylation in tumor tissues than in normal adjacent tissues, suggesting enhanced immune signaling is likely to occur during tumor development." (PMID 33953186, 2021). "The expression of SIRPA, LILRB1, LILRB2, Siglec1, Siglec7, Siglec9, PDCD1, CD163 and MARCO are preferentially expressed on Mono01, Mono02 and Macro03, suggesting their tumor-promoting roles." (PMID 40755770, 2025). "Siglec‐7 and Siglec‐9 ligands were readily detected on both the TN tumor cell lines (HCC1143, HCC1937, MDA‐MB‐231, MDA‐MB‐468) and the ER+ tumor cell lines (BT‐474, MCF7, MDA‐MB‐175, T47D)." (PMID 39246414, 2024). "While comparing between matched and unmatched tumour and normal tissue samples, upregulation of checkpoint receptor genes, notably CD47, CTLA4, HAVCR2, PVRIG, SIGLEC7, and SIGLEC9, were specifically detected in malignant compared to normal tissues." (PMID 39877370, 2024). "We explored the differential expression of the SIGLEC family in tumor and normal tissue in GEPIA and found that the content of CD22, SIGLEC7, and SIGLEC9 in the tumor was higher than that in normal tissue." (PMID 37207210, 2023). "As expected, the expression level of HAVCR2, CD40, SIGLEC7, CD86 genes are inversely correlated with tumor purity." (PMID 32021566, 2020). "It has been found that tumor cells can express sialylated ligands for SIGLEC receptors on immune cells, depressing immune cell function to escape immune surveillance, such as SIGLEC7 and SIGLEC9 on natural killer cell." (PMID 33240817, 2020). "As a ligand of SIGLEC7, total Sia, including sialylated glycolipids, gangliosides, and mucins (MUC), a highly sialylated glycoprotein family, has been demonstrated to be abundantly expressed in various types of tumor cells." (PMID 39211050, 2024). "We focus here on the critical immune checkpoint PD-1 and on Siglec-7/p75/AIRM1/CD328, LAIR-1/p40/CD305, and IRp60/CD300a, originally identified in our labs, representing additional immune checkpoints possibly dampening anti-tumor NK cell responses in given pathological settings." (PMID 33013909, 2020). "In addition to DSGb5, Siglec7 also interacts with GD3, a ganglioside expressed on tumour cells." (PMID 32322597, 2020). "Since former studies have found SIGLEC1 (CD169), SIGLEC2 (CD22), SIGLEC3 (CD33), SIGLEC7, SIGLEC9, and SIGLEC15 expressed by immune cell populations could be manipulated by tumor cells to escape immune surveillance, we focused on the five SIGLEC family members." (PMID 33240817, 2020).
cancer (13 papers, 2020 to 2025). A tumor composed of atypical neoplastic, often pleomorphic cells that invade other tissues. "To explore the association of SIGLEC7 with cancer, we employed GEPIA (Gene Expression Profiling Interactive Analysis) to compare SIGLEC7 expression levels across various tumors and their respective normal tissues." (PMID 39211050, 2024). "Consequently, molecular‐level understanding of gangliosides interaction with Siglec‐7 can not only shed light on the mechanisms underlying immune evasion in cancer, but also help the development of targeted strategies to modulate these interactions." (PMID 40285643, 2025). "Siglec7 and Siglec9 are very similar in distribution, gene encoding, protein sequences, ligand affinity, and functions in regulating the immune system against virus and cancers, but differences still exist between them." (PMID 32322597, 2020). "Siglec‐7 is an inhibitory immune receptor that is emerging as a significant target of interest for cancer immunotherapy." (PMID 40285643, 2025). "This interaction establishes Siglec‐7 and corresponding ligands as innovative glyco‐immune checkpoints in the realm of cancer treatment." (PMID 40285643, 2025). "Siglec‐7 binds the disialylated ganglioside GD3, a tumor‐associated antigen overexpressed on cancer cells to suppress immune responses." (PMID 40285643, 2025). "A wealth of evidence supports the involvement of SIGLEC7 in immune signaling, exerting inhibitory effects in regulating immune balance and serving as a checkpoint in cancer immune responses." (PMID 39211050, 2024). "Sialic acid-binding immunoglobulin-like lectin 7 (SIGLEC7) is present in various immune cells, especially macrophages, and significantly affects immune homeostasis and cancer cell response." (PMID 39211050, 2024). "In our analysis, immune inhibitory checkpoint genes, LAG3, SIGLEC7, PD-1, PD-L2, TIM3, and others, showed significantly higher expression in EMT-high samples of several cancer types." (PMID 35096592, 2021). "SIGLEC7 and other SIGLEC family genes are also potential immunotherapeutic targets against cancer." (PMID 32453742, 2020). "In addition, expression of SIGLEC-7, an inhibitory checkpoint found on natural killer (NK) cells, T cells and dendritic cells and shown to promote immune suppression when bound to sialic acids on cancer cells, was significantly higher in nonresponders than responders (P = 0.044)." (PMID 38191613, 2024).
infection (1 paper, 2023). The state of being infected such as from the introduction of a foreign agent such as serum, vaccine, antigenic substance or organism. "Given the significant association of the SIGLEC7 gene with clinical score, we explored the protein structure and function of the coding nonsynonymous SNP rs993496436 of this gene, hypothesizing that the SNP rs993496436 might be relevant for disease severity in infection with SARS-CoV-2." (PMID 37971979, 2023).
SIGLEC7 also shares sentences with these, for which no sentence is quoted: diabetes (3 papers); colorectal cancer (1); kidney chromophobe (1); nonalcoholic fatty liver disease (1); osteoporosis (1); pneumonia (1); renal cell carcinoma (1); stomach adenocarcinoma (1).